ZBTB34 (zinc finger and BTB domain containing 34)
Description:
May be a transcriptional repressor.
Synonyms: KIAA1993; MGC24652; ZNF918
Gene: Protein-coding gene on chromosome 9 (126,860,632 to 126,885,878, forward strand). Ensembl gene ENSG00000177125.
Subcellular location: Nucleus
Subcellular location (Human Protein Atlas): Nucleoplasm
Genetic constraint (gnomAD): Loss-of-function variants: 1 observed, 34.58 expected, observed/expected ratio (o/e) 0.0289, 90% interval 0.009 to 0.14. The upper end of that interval is the gene's LOEUF score, 0.14, which puts it in group 1 of 6, group 1 being the genes least tolerant of losing a copy. Missense variants: 406 observed, 692.36 expected, observed/expected ratio (o/e) 0.59, 90% interval 0.54 to 0.64. Synonymous variants: 283 observed, 267.65 expected, observed/expected ratio (o/e) 1.06, 90% interval 0.96 to 1.17.
Homologues: Orthologues: chimpanzee ZBTB34 (100% identical), macaque ZBTB34 (100% identical), dog ZBTB34 (99% identical), pig ZBTB34 (98% identical), guinea pig ZBTB34 (95% identical), rabbit ZBTB34 (94% identical), mouse Zbtb34 (93% identical), rat Zbtb34 (93% identical), tropical clawed frog zbtb34 (78% identical), zebrafish zbtb34 (60% identical). Paralogues in human: ZBTB37 (45% identical), ZNF84 (20% identical), ZNF160 (20% identical), ZNF107 (19% identical), ZNF420 (18% identical), ZNF91 (18% identical), ZNF594 (18% identical), ZNF473 (18% identical), ZNF99 (18% identical), ZNF208 (17% identical), ZNF347 (17% identical), ZNF845 (17% identical), and 24 more.
Diseases named in the same sentence as ZBTB34 in open-access papers:
ZBTB34 is named in the same sentence as 21 diseases in open-access papers, as found by Europe PMC text mining. Sharing a sentence is not in itself a finding about the gene and the disease. The quoted sentences say what the papers report.
colorectal cancer (1 paper, 2022). A primary or metastatic malignant neoplasm that affects the colon or rectum. "It was found in a recent study that Zbtb34 and lnc-CPLC strongly correlated in colorectal cancer progression, indicating that lnc-CPLC/miR-4319/Zbtb34 signal axis played a role in regulating the development of colorectal cancer." (PMID 36098743, 2022).
hepatocellular carcinoma (1 paper, 2023). A malignant tumor that arises from hepatocytes. "In conclusion, ZBTB34 is a hepatocellular carcinoma-associated protein with a monopartite NLS." (PMID 37650557, 2023).
liver cancer (1 paper, 2024). An epithelial or non-epithelial malignant neoplasm that arises from the liver. "For instance, our recent research discovered that the Zn finger protein ZBTB34 can bind to telomere DNA, regulate telomere length, and is associated with the onset of liver cancer." (PMID 38706559, 2024).
lymph node metastasis (1 paper, 2022). "A similar well-designed study aimed at identifying the genes associated with the involvement of lymph node metastasis in patients with PCa and, among 376 genes investigated, three genes, RALGPS1, ZBTB34 and GOLGA1, had a significant copy number alteration." (PMID 36077746, 2022).
tumor (2 papers, 2022 to 2023). "Zbtb34 has also been shown to play a role in tumor growth as a transcriptional repressor." (PMID 36098743, 2022). "Therefore, we believe that the other two ZnFs in Zbtb34 are involved in transcriptional repression of tumor growth." (PMID 36098743, 2022). "The correlation between ZBTB34 expression and LIHC in these five tumor types is consistent with the finding of gene expression analysis." (PMID 37650557, 2023).
cancer (1 paper, 2023). A tumor composed of atypical neoplastic, often pleomorphic cells that invade other tissues. "According to the ZBTB34 expression levels, we divided the cancer cases into high-expression and low-expression groups." (PMID 37650557, 2023). "Although there is currently little research on the mechanism of ZBTB34 in cancer, extensive data have found that ZFPs play crucial roles in the development of cancer." (PMID 37650557, 2023). "The controversial expression pattern for various cancer types indicates ZBTB34 has a complicated role in the development of cancer." (PMID 37650557, 2023). "Next, we examined the correlation between ZBTB34 expression and the pathological stages of cancers using the “Pathological Stage Plot” module of Gene Expression Profiling Interactive Analysis version 2 (GEPIA2)." (PMID 37650557, 2023). "We applied the TIMER2 approach to analyze the expression status of ZBTB34 across various cancer types." (PMID 37650557, 2023). "In this study, we analyzed ZBTB34 expression in a total of 32 different tumors based on the data of the TCGA database which is one of the largest publicly available and high-quality data sources for cancer-genomic studies." (PMID 37650557, 2023).
ZBTB34 also shares sentences with these, for which no sentence is quoted: adenoid cystic carcinoma (1 paper); Breast invasive carcinoma (1); cholangiocarcinoma (1); colon adenocarcinoma (1); endometrial carcinoma (1); esophageal carcinoma (1); head and neck squamous cell carcinoma (1); lung adenocarcinoma (1); Lung squamous cell carcinoma (1); Marfan syndrome (1); paraganglioma (1); pheochromocytoma and (1); Skin Cutaneous Melanoma (1); stomach adenocarcinoma (1); Thyroid carcinoma (1).